DNMT1 (DNA methyltransferase 1)
Diseases named in the same sentence as DNMT1 in open-access papers (continued):
Sharing a sentence is not in itself a finding about the gene and the disease.
breast cancer (continued). "Previous evidence has shown that DNMT1 is overexpressed in breast cancer, thyroid cancer cells, and pancreatic cancer." (PMID 34589490, 2021). "In many studies, in breast cancer cells incubated with curcumin, the DNMT1 protein level was significantly decreased and it was consistent with the mRNA levels of DNMT1, also significantly downregulated in curcumin-exposed cells." (PMID 33498667, 2021). "In breast cancer, circ-DNMT1, which is formed by the back splicing of the DNA methyltransferase 1 transcript, contributes to breast cancer cell proliferation and progression via the activation of cellular autophagy machinery." (PMID 33433832, 2021). "Collectively, our data indicated that DNMT1-mediated hypermethylation of KLF4 promoter leads to downregulation of KLF4 in breast cancer." (PMID 34150611, 2021). "In conclusion, this study has revealed that TINCR promotes tumorigenesis through a STAT3–TINCR–EGFR-feedback loop by recruiting DNMT1 and acting as a ceRNA in human breast cancer." (PMID 33446634, 2021). "As for the various molecular typing groups, low FOXO3a expression, or high expression of FOXM1, SOX2, and DNMT1 was relevant to shorter survival in ERα+ breast cancer patients." (PMID 31296961, 2020). "Next, we analyzed the clinicopathological implication of FOXO3a, FOXM1, SOX2, and DNMT1 levels in breast cancer patients." (PMID 31296961, 2020). "Mice under-expressing DNMT1 have global hypomethylation preceding thymic tumors, and more malignant breast cancer cells have more extensive hypomethylation and more changes in DNMT and histone methylation." (PMID 32399610, 2020). "The anticancer effects of sulforaphane were found to be mediated by a global DNA hypomethylation, decreased levels of DNMT1 and DNMT3b and changes in the microRNA profiles of the three breast cancer cells lines." (PMID 32903500, 2020). "Resveratrol has been reported to inhibit the activity of DNMT3b and DNMT1 in mammary tumors in a dose-dependent fashion." (PMID 32903500, 2020). "The decrease in BRCA1 gene promoter methylation and expression by genistein in breast cancer cells was also attributed to a decrease in DNMT1 expression both in vitro (MCF7, UACC3199, and HCC38 cell lines) and in vivo (BRCA1 F22/24 mice)." (PMID 32878338, 2020). "The authors reported that antroquinonol D can inhibit the activity of DNMT1 in MDA-MB-231 breast cancer cells with an IC50 value lower than 5 μM." (PMID 32903500, 2020). "We further investigated the clinical significance of DNMT1/FOXO3a/FOXM1/SOX2 signaling in breast cancer." (PMID 31296961, 2020). "A previous study has shown that DNMT1 with high expression greatly reverses the suppressive effects of H19 silence on cell proliferation and invasion in breast cancer." (PMID 32918845, 2020). "We next analyzed the correlation of FOXO3a, FOXM1, SOX2, and DNMT1 expression to the prognosis of breast cancer patients with lymph node metastasis status." (PMID 31296961, 2020). "We found that the combination of low FOXO3a expression and high FOXM1, SOX2, and DNMT1 expression was a strong predictor of shorter survival in breast cancer patients." (PMID 31296961, 2020). "In the current study, we found that DNMT1-mediated FOXO3a promoter hypermethylation leads to downregulation of FOXO3a expression in breast cancer, and FOXO3a suppresses BCSC properties and tumorigenicity via inhibition of FOXM1/SOX2 signaling." (PMID 31296961, 2020). "Clinically, we observed a significant inverse correlation between FOXO3a and FOXM1/SOX2/DNMT1 expression levels, and loss of FOXO3a expression or increased expression of FOXM1, SOX2, and DNMT1 predicted poor prognosis in breast cancer." (PMID 31296961, 2020). "Experimentally, increasing folate levels in breast cancer cell lines lead to increased DNMT1 levels, with promoter methylation of PTEN and its downregulation (and cancer progression)." (PMID 32582754, 2020).
breast cancer (continued). "A similar effect was observed in MCF7 and MDA-MB-231 breast cancer cell lines where exposure to 10 μM SFN reduced DNMT1 expression and elevated the expression of PTEN and RARβ2 via promoter demethylation, thus enhancing cell growth arrest and apoptosis." (PMID 32878338, 2020). "The over-expression of DNMTs (DNMT1, 3A, and 3B) has been shown in uterine cancer, breast cancer, hepatocellular carcinoma (HCC), colorectal and stomach cancer." (PMID 32592383, 2020). "We found that, in general, adjacent normal tissues exhibited relatively high FOXO3a expression and very low expression of FOXM1, SOX2, and DNMT1; in contrast, breast cancer tissues had low FOXO3a, but high FOXM1, SOX2, and DNMT1 expression." (PMID 31296961, 2020). "Ralhan and co-workers showed that genistein is able to induce a significant decrease in the transcript levels of all the DNMTs including DNMT1, DNMT3a, and DNMT3b, in breast cancer." (PMID 32903500, 2020). "To establish the potential roles of the various DNMTs in mediating FOXO3a promoter methylation in breast cancer, we knocked down DNMT1, DNMT3A, and DNMT3B in breast cancer cells using specific small interfering RNAs (siRNAs)." (PMID 31296961, 2020). "Drug-induced inhibition of ERRα by C29 in the mouse cell lines NIC-5231 and NIC-5257, derived from ErbB2-driven mammary tumors, also led to a stark reduction in DNMT1 protein." (PMID 32855526, 2020). "Chlorogenic acid has been shown to inhibit DNMT1, using breast cancer cell lines, which lowers DNA methylation." (PMID 33312959, 2020). "Here, we report that DNMT1-mediated FOXO3a promoter hypermethylation leads to downregulation of FOXO3a expression in breast cancer." (PMID 31296961, 2020). "Laccaic acid A is a direct, competing DNMT1 natural compound inhibitor that reactivates genes silenced by promoter DNA methylation synergistically with 5-azadC in breast cancer cells." (PMID 33312959, 2020). "Using breast cancer cell lines, it was demonstrated that chlorogenic acid inhibits DNMT1, curbing DNA methylation." (PMID 32365701, 2020). "circDNMT1 interacted with AUF1 and facilitated the nuclear translocation of AUF1, relieving DNMT1 mRNA from AUF1 induced instability of DNMT1 mRNA in breast cancer." (PMID 33643900, 2020). "Taken together, these findings indicated that dysregulated FOXO3a/FOXM1/SOX2/DNMT1 signaling plays a critical role in disease progression and is a valuable biomarker in breast cancer." (PMID 31296961, 2020). "Transfection of circ-Dnmt1 into breast cancer cells can induce autophagy to maintain cell homeostasis and ultimately promote cell proliferation and tumorigenesis." (PMID 32670861, 2020). "Another study demonstrated that FEN1 promoted breast cancer cell proliferation via an epigenetic mechanism whereby FEN1-mediated up-regulation of DNMT1 and DNMT3a." (PMID 31534853, 2019). "Our current work shows that OCT4 requires ERα to suppress the proliferation of breast cancer cells through the DNMT1/ISL1/ERK axis, providing a novel molecular circuit for inhibiting BCC proliferation." (PMID 31012189, 2019). "OCT4 is dependent on ERα to suppress the proliferation of breast cancer cells through DNMT1/ISL1/ERK axis." (PMID 31012189, 2019). "SFN treatment downregulates hTERT and reduces DNA methyltransferase 1 (DNMT1) and DNA methyltransferase 3a (DNMT3a) in human breast cancer cells." (PMID 31186051, 2019). "The levels of DNMT-1, -3a, and -3b are generally upregulated in sporadic breast cancer and correlates with a poor prognosis; elevated DNMT1 level associates with lymph node metastasis, while DNMT3a and DNMT3b are associated with aggressive stages." (PMID 31426393, 2019). "Our group reported that resveratrol modulated the methylation status of a specific broad set of genes independently of DNMT1 inhibition in MDA-MB-231 breast cancer cells." (PMID 30881375, 2019).
breast cancer (continued). "Genistein was associated with the reactivation of estrogen receptor-α (ERα) as a consequence of lowered expression of DNMT1 in a breast cancer experimental model in virgin female immunodeficiency nu/nu mice." (PMID 31323834, 2019). "Using a candidate gene approach, we identified the DNMT1 SNP rs2162560 from the literature and evaluated its association with CACI in a cohort of breast cancer patients." (PMID 31601979, 2019). "In breast cancer, increased DNMT1 expression lowers DNMT1 expression and contributes to enhanced hyperactivation of the PI3K/AKT and ERK pathways that promote tumor growth." (PMID 31723119, 2019). "The aberrant global DNA hypermethylation induced by ERα enhanced anticancer drug resistance in human breast cancer cells by activating the DNMT1 gene." (PMID 30670062, 2019). "A study using the TumorGraft mouse model found that global DNA methylation and DNMT1 levels decreased in the pre-frontal cortex of mice with triple-negative or progesterone-positive breast cancer TumorGrafts36." (PMID 31601979, 2019). "This study investigates the association between a DNMT1 polymorphism, rs2162560, and chemotherapy-associated cognitive impairment (CACI) in a cohort of breast cancer patients." (PMID 31601979, 2019). "In our previous study, antroquinonol D inhibited MDA-MB-231 breast cancer cell growth and induced DNA demethylation, likely through the inhibition of DNA methyltransferase 1 activity." (PMID 30308939, 2018). "This indicates that BSFs that express high level of DNMT1 can paracrinally enhance the EMT process in breast cancer cells." (PMID 29416775, 2018). "The major finding of the present study is that miR-506 inhibits migration and invasion of breast cancer cell lines through an undescribed pathway SP1/SP3/DNMT1/MEG3." (PMID 30386180, 2018). "To address the role of DNMT1 in BSFs, we first assessed the level of DNMT1 in breast cancer tissues." (PMID 29416775, 2018). "The DNA methyltransferase 1 inhibitor, 5-Aza-2′-deoxycytidine (5-Aza-dC) is a potential treatment for breast cancer." (PMID 30002602, 2018). "Assessment of DNMT1 in breast cancer tissues showed that DNMT1 is highly expressed in TNBC compared with other subtype." (PMID 30547810, 2018). "Next, we sought to investigate the paracrine effects of BSFs that express high levels of DNMT1 on breast cancer cells." (PMID 29416775, 2018). "The present data demonstrate the critical function of DNMT1 in breast cancer-related sustained activation of breast stromal fibroblasts." (PMID 29416775, 2018). "Here, we show that miR-506 inhibits migration and invasion of breast cancer cell lines through the SP3/DNMT1/MEG3 axis." (PMID 30386180, 2018). "Another study reported that the anticancer effect of genistein on breast carcinoma can be because of its ability of demethylation and reactivation of methylation-silenced TSGs by interacting with the DNMT1 catalytic domain and blocking the expression of DNMT1." (PMID 29681985, 2018). "Nine genes in this module – Akt1, Brca2, Ccnd1, Dnmt1, Mki67, Palb2, Rrm1, Timeless, and Top2a – are known human breast cancer genes according to the MalaCards database; four of them are hub genes." (PMID 28212608, 2017). "Ectopic excess of miR-152 prevents migration of breast cancer cells, for miR-152 targeting DNMT1 mRNA and inhibits its protein expression." (PMID 28167852, 2017). "It has been demonstrated that GS treatment of breast cancer cells inhibits the expression of DNA (cytosine-5)-methyltransferase 1(DNMT1) and HDAC1." (PMID 28261317, 2017). "As described in Section 3.2, H19 impairs availability of miR-152 and increases the expression of the epigenetic regulator DNMT1 and so increases proliferation of breast cancer cells lines." (PMID 29099749, 2017). "A number of publications describe a decrease in DNMT1 at both the mRNA level and protein level with Trichostatin A treatment in cancer models including; hepatocellular, bladder and breast cancer cell lines." (PMID 28881658, 2017).
breast cancer (continued). "In human breast cancer cells lines, H19 upregulates the DNA methyltransferase DNMT1 by sponging miR-152, leading to enhancement of cell proliferation and invasion of the cells." (PMID 29099749, 2017). "Currently, the possibility of DNMT1 as a new target is being explored for many tumors and DNMT1 can be a new target for breast cancer as well." (PMID 27071379, 2016). "Our results strongly confirm that ERα can activate DNMT1 and DNMT3b genes by direct binding to the gene promoters in breast cancer cells." (PMID 26980709, 2016). "A clinicopathologic study showed that the level of DNMT1 is significantly higher in sporadic breast cancer tissue than in breast fibroadenoma." (PMID 27525019, 2016). "Herein, we explored the effects of THL in MCF-7 breast cancer cells that also demonstrate elevated DNMT1." (PMID 27525019, 2016). "This notion is also supported by our previous observations that only DNMT1 expression was positively correlated with global DNA methylation level in two PTX-resistant breast cancer cell lines, MCF-7/PTX and MDA-MB-231/PTX." (PMID 26980709, 2016). "Tumor expression of DNMT1 in breast cancer differed by molecular subtype and stromal histological type." (PMID 27071379, 2016). "This important observation provides validity for a novel concept and strategy in the treatment of breast cancer via the targeting of DNMT1." (PMID 27525019, 2016). "Previous studies of epigenetic methylation-related proteins in breast cancer found that expression of DNMT1 and DNMT3a is higher in breast cancer than in benign lesions and the expression is related to breast cancer prognosis." (PMID 27071379, 2016). "Estrogen enhanced multi-drug resistance of breast cancer cells by up-regulating DNMT1 and DNMT3b expression." (PMID 26980709, 2016). "It implies that DNMT1 plays a significant role in de novo DNA methylation in breast cancer cells in addition to its function in maintaining DNA methylation." (PMID 26980709, 2016). "Another indication of ERα involvement in epigenetic regulation from our previous work is that ERα significantly up-regulated DNMT1-luciferase reporter gene activity in breast cancer cells." (PMID 26980709, 2016). "Silencing of GSK‐3β by shRNA prevented histone H3 phosphorylation and reduced DNMT1 expression so that can restrain breast cancer cell proliferation." (PMID 27060477, 2016). "Our data demonstrated that ERα propelled aberrant global DNA hypermethylation by activating the DNMT1 gene to enhance anticancer drug resistance in human breast cancer cells." (PMID 26980709, 2016). "DNMT1 expression is confirmed to be positively correlated with ERα expression in the breast cancer tissues." (PMID 26980709, 2016). "Numerous studies demonstrate the crucial role of DNMT1 in various types of cancers, including acute myeloid leukemogenesis, breast cancer, prostate cancer, pancreatic cancer, lung cancer." (PMID 27286455, 2016). "Our data demonstrated that ERα increased the drug-induced global DNA hypermethylation through activation of the DNMT1 gene to enhance the anticancer drug resistance of breast cancer cells." (PMID 26980709, 2016). "The notion was supported by the positive correlation between DNMT1 and ERα expression (P=0.046) detected by our immunohistochemical analysis in 78 breast cancer tissues samples." (PMID 26980709, 2016). "In support of these observations, estrogen enhanced multi-drug resistance of breast cancer cells by up-regulation of DNMT1 and DNMT3b genes." (PMID 26980709, 2016). "In conclusion, DNMT1 is differentially expressed in breast cancer according to the molecular and stromal subtypes, and it is most highly expressed in TNBC and inflammatory stromal types." (PMID 27071379, 2016). "It is notable that over-expression of DNMT1 alone doubles the global DNA methylation level in breast cancer cell lines examined and knockdown of DNMT1 significantly blocks the ERα-induced global DNA hypermethylation." (PMID 26980709, 2016).
breast cancer (continued). "Taken together, our study demonstrated that the dietary compound ISL prevents mammary carcinogenesis by inhibiting breast cancer stem cells through DNMT1-mediated WIF1 demethylation." (PMID 25918249, 2015). "Taken together, our findings discovered a novel function of ISL as a natural DNMT1 inhibitor to prevent breast cancer by targeting the aberrant WIF1 signaling." (PMID 25918249, 2015). "In this study, we found that δEF1 bound to DNMT1 in breast cancer cells of the basal-like subtype, and that silencing of δEF1 family proteins (δEF1/ZEB1 and SIP1/ZEB2) considerably decreased the number of 5mC sites." (PMID 25315069, 2015). "The expression of several DNA methyl transferases (DNMT1, DNMT3a, and DNMT3b) has been found to be elevated in breast cancer tissue." (PMID 26694341, 2015). "Among these enzymes, over-expression of Dnmt3b have been found in the tumor tissues of approximately 30% of breast cancer patients, whereas Dnmt1 and Dnmt3b are over-expressed in approximately 5% and 3% of breast tumors." (PMID 25928539, 2015). "Sustained knockdown of δEF1 family proteins reduced the number of 5mC sites in the E-cadherin promoter region, suggesting that these proteins maintain 5mC through interaction with DNMT1 in breast cancer cells." (PMID 25315069, 2015). "Other studies show that zebularine decreases levels of DNMT1, DNMT3a, and DNMT3b in breast cancer cell lines as well as DNMT1 and partially DNMT3b in bladder cancer cells." (PMID 26161298, 2014). "Selective depletion of DNMT1 was reported to reactivate expression of CDKN2A/p16 in HCT116 colon cancer cells and re-expression of CDKN2A/p16 after knockdown of DNMT1 in human lung and breast cancer cells." (PMID 25340937, 2014). "Our findings imply that genetic (such as BRCA1 mutation) and epigenetic mechanisms (such as DNA methylation, histone modification, transcription factor binding) are jointly involved in the malignant progression of DNMT1-related breast cancer." (PMID 24502362, 2014). "We identified one additional statistically significant correlation for DNMT1 SNP (A201G, rs2228612), which appears to protect women against developing breast cancer." (PMID 23638630, 2013). "Recently, direct relation between DAC-induced DNMT1 depletion and p21WAF1 induction was observed in drug-resistant breast cancer cells (MCF-7/ADR)." (PMID 24000324, 2013). "In the case–control study presented herein, we correlated genetic polymorphisms in three genes, DNMT1, DNMT3A and DNMT3B, with clinical parameters to consider the risk of female Caucasians developing breast cancer." (PMID 23638630, 2013). "The expression of DNMT1 is regulated by microRNAs (in breast cancer tissues microRNAs are globally downregulated) and the methyltransferase activity is reduced by phosphorylation of DNMT1." (PMID 23638630, 2013). "The positive expression of DNMT1 in the 100 breast cancer samples was 69% (69/100), which was significantly greater than that in the breast FA tissues 32% (7/22), (P = 0.001)." (PMID 22455563, 2012). "Consistent with previous findings that SFN decreased expression of DNMT1 and DNMT3a in breast cancer cells, SFN also decreased DNMTs expressions in our study." (PMID 22303414, 2011). "TMEFF2 had previously been reported to be methylated in lung adenocarcinoma, and inactivation of DNA methyltransferase 1 in a breast cancer cell line reactivates methylated TMEFF2, suggesting its DNA methylation leads to silencing." (PMID 21731750, 2011). "Another important discovery of this study is that SFN reduced DNMTs (DNMT1 and DNMT3a) activity in human breast cancer cells." (PMID 20625516, 2010). "To our surprise, we discovered that SFN can considerably inhibit DNMT1 and 3a expression in a dose-dependent manner in human breast cancer cells and the inhibition was less in normal MCF10A cells." (PMID 20625516, 2010).